NR1D1 (nuclear receptor subfamily 1 group D member 1)
Diseases named in the same sentence as NR1D1 in open-access papers (continued):
Sharing a sentence is not in itself a finding about the gene and the disease.
lung carcinoma (5 papers, 2018 to 2024). "For example, studies in the model of lung cancer found that Nr1d1 deficiency promoted tumorigenesis by increasing NLRP3 inflammasome activation and pro-inflammatory cytokine production, potentially mediated in part through the downregulation of NRF2." (PMID 39199147, 2024). "Treatment with MCC950, a specific inhibitor of NLRP3 inflammasome, blocked tumorigenesis in NR1D1-deficient mice in an orthotopic lung cancer model." (PMID 37524704, 2023). "In the present study, we found that the activation of the NLRP3 inflammasome in the NR1D1-deficient TME plays a crucial role in lung cancer development and EMT." (PMID 37524704, 2023). "In conclusion, we showed that NR1D1 deficiency in the TME promotes lung cancer development and metastatic potential through NLRP3 inflammasome activation." (PMID 37524704, 2023). "In this study, we attempted to verify the anti-tumor efficacy of SR9009, one of the NR1D1 agonists, in lung cancer." (PMID 37524704, 2023). "Although the tumor suppressive role of NR1D1 in lung cancer development was clearly observed in this study, the role of NR1D1 in other types of cancer remains to be elucidated." (PMID 37524704, 2023). "This study is the first to elucidate the role of NR1D1 in lung cancer development through in vivo experiments using genetically engineered mice and in vitro experiments, which will contribute to our understanding of the biological role of NR1D1." (PMID 37524704, 2023). "Finally, further investigation of NR1D1’s role in the TME will propose a therapeutic strategy to overcome lung cancer." (PMID 37524704, 2023). "Our results suggest that NR1D1 acts as a tumor suppressor in lung cancer development, indicating that NLRP3 inflammasome blockade via NR1D1 activation could be a therapeutic option for lung cancer patients." (PMID 37524704, 2023). "NR1D1-deficient mice showed increased NACHT, LRR, and PYD domain-containing protein 3 (NLRP3) inflammasome activation, and conditioned medium (CM) from NR1D1-deficient macrophages increased the proliferation and epithelial–mesenchymal transition (EMT) of lung cancer cells." (PMID 37524704, 2023). "In our orthotopic lung cancer model, pleural metastasis was more prominently observed in LLC1-injected Nr1d1−/− mice than in LLC1-injected WT mice." (PMID 37524704, 2023). "Although several reports suggest that NR1D1 functions as a tumor suppressor, its role of NR1D1 in lung cancer development has not been clearly elucidated." (PMID 37524704, 2023). "Our results showed that NR1D1 in the tumor microenvironment functions as a tumor suppressor by negatively regulating the NLRP3 inflammasome, suggesting that the NLRP3 inflammasome blockade via NR1D1 activation could be a therapeutic strategy to overcome lung cancer." (PMID 37524704, 2023). "However, as the role of NR1D2 in lung cancer is not known to date, we cannot exclude the possibility that NR1D2 acts as a tumor suppressor in lung cancer, similar to NR1D1." (PMID 37524704, 2023).
mental disorder (5 papers, 2014 to 2024). A disease that has its basis in the disruption of mental process. "Probably, this change in Nr1d1 expression in MS females and the related possible aberration of circadian rhythms may explain greater susceptibility to psychiatric disorders at an adult age." (PMID 32190129, 2020).
mood disorder (5 papers, 2013 to 2024). A cognitive disorder a disturbance in which the person's mood is hypothesized to be the main underlying feature. "According to clinical observations, patients with mood disorders often have the abnormalities in a circadian rhythm that correlate with nucleotide substitutions in various circadian clock genes including NR1D1." (PMID 36769363, 2023).
retinal degeneration (5 papers, 2011 to 2023). Degeneration of the retina. "Our findings uncover NR1D1 as a potential therapeutic target for Nr2e3 associated retinal degeneration that can compensate for Nr2e3 loss by regulating key molecular pathways associated with disease." (PMID 24498227, 2014). "In this study we demonstrate that the nuclear hormone receptor gene Nr1d1 (Rev-Erbα) rescues Nr2e3-associated retinal degeneration in the rd7 mouse, which lacks a functional Nr2e3 gene." (PMID 24498227, 2014). "In the present study, we show that Nr1d1 is a genetic modifier able to ameliorate Nr2e3 associated retinal degeneration and confirm that NR1D1 and NR2E3 act synergistically to regulate genes involved in retinal development and function." (PMID 24498227, 2014). "Here, we demonstrate that in vivo delivery of the candidate modifier gene, Nr1d1 rescues Nr2e3 associated retinal degeneration." (PMID 24498227, 2014). "Future studies will focus on exploring the applicability of using Nr1d1 gene delivery for treating Nr2e3-associated retinal degeneration at advanced stages of disease, as well as retinal disease with other genetic causes." (PMID 24498227, 2014). "We therefore hypothesized that NR1D1 is able to suppress rd7 associated retinal degeneration through molecular rescue of key developmental and functional pathways that are misregulated in the rd7 retina." (PMID 24498227, 2014). "Thus, Nr1d1 is a strong candidate to modify the effects of Nr2e3-associated retinal degeneration." (PMID 24498227, 2014). "The NHR 1 family d, member 1 (Nr1d1), a NHR gene, and cofactor of Nr2e3, was identified as one of the genetic modifiers that can ameliorate Nr2e3 associated retinal degeneration." (PMID 32123325, 2021). "Together, these findings reveal the potency of nuclear receptors as modulators of disease and specifically of NR1D1 as a novel therapeutic for retinal degenerations." (PMID 24498227, 2014). "Our previous studies show that acute knockdown of NR1D1 by shRNA targeting in the mouse retina results in retinal degeneration similar to that observed in rd7 animals." (PMID 24498227, 2014). "Studies have confirmed that NR1D1 reverses the functional NR2E3 gene in retinal degeneration mice." (PMID 37740201, 2023). "In vivo electroporation was performed to deliver Nr1d1 alleles from either C57BL/6J or AKR/J into the retina of neonatal rd7 mice and determine whether NR1D1 can modulate rd7 associated retinal degeneration." (PMID 24498227, 2014). "Although no human mutations in NR1D1 have yet been reported in association with retinal degeneration, few studies have examined patients for mutations in this gene." (PMID 21408158, 2011). "Therefore, NR1D1 can be used as a new therapeutic drug for retinal degeneration." (PMID 37740201, 2023). "Interestingly, our real time PCR results revealed that RP models showed very low to no expression of Nr2e3 and other key transcription factors evaluated in this study (Nrl, Crx, Trb, Rora, and Nr1d1), which likely contributed to the progression of retinal degeneration in each model." (PMID 32123325, 2021). "Additionally, our studies only examined injected mice at P30.5 and lack of Nr1d1 may result in slow or delayed retinal degeneration." (PMID 21408158, 2011).
glioblastoma (4 papers, 2014 to 2025). The most malignant astrocytic tumor (WHO grade IV). "To further probe the role of the circadian clock in treatment response, we generated CRISPR-Cas9 knockouts (KOs) of three key clock components—BMAL1, PER2, and NR1D1—in the T98G glioblastoma cell line." (PMID 41387951, 2025).
Hyperglycemia (4 papers, 2019 to 2022). An increased concentration of glucose in the blood. "Thus, decreased expression of Nr1d1 in the hypothalamus might be linked to hyperglycemia in the GK rat." (PMID 31579613, 2019). "Based on previous studies, we found the dysregulations of Plin2, Alox15, Nr1i2, and Nr1d1 genes related to lipid metabolism might implicate to the disorders of the hypothalamus in the diabetic GK rats and contribute to the hyperglycemia in them." (PMID 31579613, 2019).
lung adenocarcinoma (4 papers, 2022 to 2023). A carcinoma that arises from the lung and is characterized by the presence of malignant glandular epithelial cells. "Downregulation of NR1D1 significantly enhances NF-κB transcription, stimulates invasion and promotes proliferation of the lung adenocarcinoma cell line A549." (PMID 38072952, 2023). "Moreover, hepatic protein kinase A (PKA) signaling is activated by an increase in glucagon and destabilizes NR1D1, resulting in increased glucose production in a lung adenocarcinoma cachexia model." (PMID 38072952, 2023).
ovarian carcinoma (4 papers, 2021 to 2024). A malignant neoplasm originating from the surface ovarian epithelium. "Our study showed that NR1D1 arrested cell cycle at G1 phase and decreased the levels cell cycle-associated proteins, such as cyclins, indicating that cell cycle arrest induced by NR1D1 may contribute to its role in ovarian cancer growth." (PMID 34330232, 2021). "Here we provide strong data showing that NR1D1 is a DDR repressor in ovarian cancer cells as well, but that this regulation occurs through a direct interaction of NR1D1 with both PARP1 and BRCA1." (PMID 34743206, 2022). "Nuclear receptor subfamily 1 group D member 1 (NR1D1), a nuclear receptor associated with a variety of physiological processes, has a low level in ovarian cancer tissues compared with adjacent normal tissues." (PMID 34330232, 2021). "Herein, we explored the function of NR1D1 on the growth of ovarian cancer cells and the activation of SOCS3/JAK/STAT3 signaling pathway." (PMID 34330232, 2021). "Over-expression of NR1D1 retarded the proliferation of ovarian cancer cells, while NR1D1 silencing accelerated their growth, suggesting that NR1D1 suppresses the growth of ovarian cancer cells." (PMID 34330232, 2021). "Up-regulation of NR1D1 repressed the ovarian cancer cell proliferation and induced cell cycle arrest and apoptosis, while silencing NR1D1 promoted their proliferation and G1/S transition." (PMID 34330232, 2021). "According to data from gene expression profiling interactive analysis (GEPIA) website based on the Cancer Genome Atlas (TCGA) data, NR1D1 is lowly expressed in ovarian cancer tissues." (PMID 34330232, 2021). "It was indicated that silencing SOCS3 abolished the function of NR1D1 over-expression on the proliferation and apoptosis of ovarian cancer cells as well as the activation of STAT3 signal." (PMID 34330232, 2021). "First, the NR1D1 level in ovarian cancer cell lines COC1, SK-OV3, OVCAR3, A2780 and a normal ovarian epithelial cell NOEC was determined by qRT-PCR and western blot." (PMID 34330232, 2021). "Based on data from TCGA, the GEPIA website showed that NR1D1 expression in ovarian cancer is lower than the normal tissues." (PMID 34330232, 2021). "Whereas, SOCS3 silencing abolished the function of NR1D1 over-expression on ovarian cancer growth and JAK/STAT3 signaling pathway." (PMID 34330232, 2021). "Our study showed that NR1D1 suppressed the proliferation and induced apoptosis of ovarian cancer cells." (PMID 34330232, 2021). "Based on our finding showing a prognostic value of Ran and NR1D1 in the context of ovarian cancer, we investigated whether this miRNA was correlated with patient survival using the KM plotter tool." (PMID 34743206, 2022). "The role of NR1D1 in the growth of ovarian cancer cells was also explored in vivo." (PMID 34330232, 2021). "As SOCS3 has a low expression level in ovarian cancer tissues and positively correlated with the level of NR1D1, we speculate that NR1D1 may influence the JAK/STAT3 signaling pathway as well as ovarian cancer cell growth through modulating SOCS3." (PMID 34330232, 2021). "As chemotherapeutic drugs for ovarian cancer treatment also promote the generation of ROS, we speculate that NR1D1 may also influence the chemoresistance of ovarian cancer cells." (PMID 34330232, 2021). "Ovarian cancer cell lines showed a lower NR1D1 level than NOEC." (PMID 34330232, 2021). "On the other hand, apoptosis was induced by NR1D1 over-expression, which may contribute to the tumor-suppressor role of NR1D1 in ovarian cancer." (PMID 34330232, 2021). "The level of NR1D1 in ovarian cancer cells was determined by quantitative real-time PCR." (PMID 34330232, 2021). "In our study, the JAK/STAT3 signaling pathway was inhibited by NR1D1 over-expression and enhanced by NR1D1 silencing, indicating that the JAK/STAT3 signal may be implicated in the role of NR1D1 in ovarian cancer cells." (PMID 34330232, 2021). "Herein, we investigated the function of NR1D1 in ovarian cancer." (PMID 34330232, 2021).
ovarian carcinoma (continued). "Our results highlight a profound role for NR1D1 in ovarian cancer." (PMID 34330232, 2021). "This study highlights a profound role of NR1D1 in the treatment of ovarian cancer." (PMID 34330232, 2021). "A xenograft model of ovarian cancer was established to explore the role of NR1D1 in vivo." (PMID 34330232, 2021). "In the present study, we explored the function of NR1D1 in ovarian cancer." (PMID 34330232, 2021). "Additionally, silencing SOCS3 abolished the effect of NR1D1 over-expression on the proliferation and apoptosis of ovarian cancer cells, confirming that NR1D1 performs its role in ovarian cancer cells through modulating the expression of SOCS3." (PMID 34330232, 2021). "NR1D1 shRNAs decreased the level of NR1D1 in ovarian cancer cells." (PMID 34330232, 2021). "In addition, shRNAs for NR1D1 were transfected into SK-OV-3 cells, which showed the highest NR1D1 level in ovarian cancer cell lines." (PMID 34330232, 2021). "Interestingly, the level of SOCS3 was positively correlated to NR1D1 in ovarian cancer according to data from GEPIA." (PMID 34330232, 2021). "We wonder how NR1D1 influences the JAK/STAT3 signal in ovarian cancer cells." (PMID 34330232, 2021). "Hence, we wonder what the function of NR1D1 is in ovarian cancer cells." (PMID 34330232, 2021). "Also, according to data from TCGA, NR1D1 has a low level in ovarian cancer tissues." (PMID 34330232, 2021). "Hence, we hypothesize that activation of NR1D1 may be beneficial to the treatment of ovarian cancer." (PMID 34330232, 2021). "Another research has shown that NR1D1 inhibits activation of the JAK/STAT3 signaling pathway by upregulating the expression of SOCS3, thus suppressing ovarian cancer cell growth and inducing apoptosis." (PMID 35481240, 2022). "NR1D1 up-regulated the expression of SOCS3, resulting in suppression of the JAK/STAT3 signaling pathway, thus retarding the growth of ovarian cancer cells." (PMID 34330232, 2021). "To explored the function of NR1D1 in ovarian cancer, we employed GEPIA website to analyze the NR1D1 expression in ovarian cancer tissues (n = 426) and normal tissues (n = 88)." (PMID 34330232, 2021). "However, whether SOCS3/JAK/STAT3 is implicated in the role of NR1D1 in ovarian cancer remains not yet clear." (PMID 34330232, 2021). "Our study revealed that NR1D1 inhibited the activation of JAK/STAT3 signaling pathway through up-regulating SOCS3, thus suppressing proliferation and inducing apoptosis of ovarian cancer cells." (PMID 34330232, 2021). "Surprisingly, we showed that even in the presence of a PARPi, NR1D1 overexpression was able to significantly inhibit HR, suggesting that the regulation of DNA repair by NR1D1 in ovarian cancer is not solely dependent on PARP1." (PMID 34743206, 2022). "Data from TCGA showed that NR1D1 has a low expression level in ovarian cancer tissues, whereas, its role in ovarian cancer is not yet clear." (PMID 34330232, 2021).
type 2 diabetes (4 papers, 2016 to 2024). "As a crucial component in the regulation of circadian rhythms, NR1D1 is closely associated with type 2 diabetes, tumors, metabolic disorders, and inflammatory diseases." (PMID 39640258, 2024). "mRNA levels for NR1D1 were higher in the type 2 diabetes group (p<0.05), which was due to differences among the older participants but not in the younger subgroup, but NR1D1 protein levels were unchanged vs healthy participants." (PMID 38981930, 2024). "Our data demonstrate a dysregulation of the molecular clock system in PBMCs from participants with type 2 diabetes, manifested by a decrease in CLOCK, CRY1, p-BMAL1 and PER2 protein levels and an increase in BMAL1 and NR1D1 mRNA levels." (PMID 38981930, 2024). "Participants with type 2 diabetes showed increased BMAL1 and NR1D1 mRNA levels and decreased protein levels of circadian locomotor output cycles kaput (CLOCK), cryptochrome 1 (CRY1), phosphorylated basic helix-loop-helix ARNT like 1 (p-BMAL1) and period circadian protein homologue 2 (PER2)." (PMID 38981930, 2024).
Hypertension (3 papers, 2021 to 2025). The presence of chronic increased pressure in the systemic arterial system. "While prior research has indicated that Nr1d1 activation exerts inhibitory effects on the progression of spontaneous hypertension, our investigations have yielded unexpected and profound insights into the role of Nr1d1 in the context of IH-induced PH." (PMID 39472573, 2024).
liver cancer (3 papers, 2021 to 2026). An epithelial or non-epithelial malignant neoplasm that arises from the liver. "Conversely, the expression levels of ARNTL, NR1D1, PER1, PER2, PER3, PRKAG2, and RORA were not significantly related to the OS of liver cancer patients." (PMID 34149816, 2021).
liver disease (3 papers, 2021 to 2025). "As shown in the heat map, male offspring exposed to HSD exhibited differential expression of ten genes associated with liver disease compared to normal offspring: Ager, Dph1, Steap4, Nfe2l1, Ppara, Rbmx, Nr1d1, Ccar2, Axl, and Abcg5." (PMID 41036197, 2025).
osteoarthritis (3 papers, 2020 to 2024). A noninflammatory degenerative joint disease occurring chiefly in older persons, characterized by degeneration of the articular cartilage, hypertrophy of bone at the margins and changes in the synovial membrane. "NR1D1 is overexpressed in osteoarthritis, in which it negatively regulates the expression of OPG and decreases osteoblasts differentiation." (PMID 36923414, 2023).
periodontitis (3 papers, 2022 to 2025). An acute or chronic inflammatory process that affects the tissues that surround and support the teeth. "Periodontitis in adults resulted in decreased levels of CSNK1D, RORA, CLOCK, DBP, NR1D1, ID2, and PER3 and a substantial increase in expression of FOS." (PMID 36472983, 2022).
prostate carcinoma (3 papers, 2022 to 2025). A carcinoma that arises from epithelial cells of the prostate gland. "In prostate cancer, elevated NR1D1 expression and nuclear REV-ERBα protein overexpression is significantly associated with metastasis." (PMID 39383000, 2024).
retinal disease (3 papers, 2011 to 2021). "Examination of more patient cohorts may find mutations in NR1D1 associated with retinal disease." (PMID 21408158, 2011). "The function of genetic modifiers of NR2E3, such as the nuclear hormone receptor Nr1d1 (Rev-erbα), has been explored as a therapeutic option in the NR2E3-associated retinal disease, rd7, mouse model." (PMID 32679203, 2021).
sarcopenia (3 papers, 2025). Progressive decline in muscle mass due to aging which results in decreased functional capacity of muscles. "However, the causality of the association between the circadian timing system of the liver and sarcopenia variables was not demonstrated, and the effects included both gene upregulation (Per, Cry, Nr1d1, Nr1d2, and Dbp) and downregulation (Bmal1 and Npas2)." (PMID 39747789, 2025).
age-related macular degeneration (2 papers, 2023 to 2025). Age-related loss of vision in the central portion of the retina (macula), secondary to retinal degeneration. "In another study, activation of NR1D1 resulted in attenuation of retinal pigment epithelial and retinal damage and countered oxidative stress in age-related macular degeneration murine model." (PMID 40027191, 2025).